MMP28 (matrix metallopeptidase 28)
Diseases named in the same sentence as MMP28 in open-access papers (continued):
Sharing a sentence is not in itself a finding about the gene and the disease.
pulmonary fibrosis (6 papers, 2015 to 2025). Chronic progressive interstitial lung disorder characterized by the replacement of the lung tissue by connective tissue, leading to progressive dyspnea, respiratory failure, or right heart failure. "Matrix metalloproteinase-28 (MMP-28) has also been identified as a regulator of macrophage polarization, with its deficiency limiting M2 polarization and conferring protection against bleomycin-induced pulmonary fibrosis." (PMID 40607394, 2025). "CpG-binding domain 2 (MBD2) and matrix metalloproteinase 28 (MMP28) are two proteins that promote M2 polarization in pulmonary fibrosis." (PMID 37234611, 2023). "Several recent studies have examined the role of MMP28 in the development and progression of pulmonary fibrosis, effects that appear to be mediated through the regulation of pulmonary macrophage phenotype." (PMID 25852818, 2015). "M1 macrophages induced by MMP28 gene knockout attenuate the bleomycin-induced lung fibrosis." (PMID 33604393, 2021). "In both cohorts, serum concentrations of MMP28 were significantly higher in IPF versus non-IPF (mostly with lung fibrosis associated to autoimmune diseases and chronic hypersensitivity pneumonitis) and healthy controls (ANOVA, p<0.0001)." (PMID 30208119, 2018). "Furthermore, CAV1 and several other fibrosis associated cytokines and proteins, including IL-33, IL-9 and MMP28 regulate macrophage differentiation in pulmonary fibrosis in mice." (PMID 25852818, 2015).
hepatocellular carcinoma (5 papers, 2020 to 2023). A malignant tumor that arises from hepatocytes. "Multivariate analysis identified the association of MMP28 with a poor prognosis in hepatocellular carcinoma." (PMID 37835389, 2023). "For example, matrix metalloproteinase 28 (MMP28) enhances epithelial-mesenchymal transition (EMT) and promotes hepatocellular carcinoma metastasis via activating Notch3 Signaling." (PMID 37853162, 2023).
lung adenocarcinoma (5 papers, 2008 to 2024). A carcinoma that arises from the lung and is characterized by the presence of malignant glandular epithelial cells. "Illman and colleagues found that lung adenocarcinoma cells that expressed recombinant MMP28 showed this transition with a loss of cell surface E-cadherin, and showed proteolytic processing of latent TGFβ complexes with a resulting increased level of active TGFβ." (PMID 20003223, 2009). "Transient activity of MMP28 (Matrix Metalloproteinase 28) in A549 lung adenocarcinoma cells also induces TGF-β-dependent EMT (Epithelial-to-Mesenchymal Transition), leading to atypical proliferation and invasive tendencies of cancer cells." (PMID 38782818, 2024). "Secretion of MMP-28 into conditioned media as a furin-cleaved protein (Mr-48 kDa) has been reported with human HT1080 fibrosarcoma, HeLa cervical cancer cells and A549 lung adenocarcinoma cells transfected with mouse MMP-28 cDNA." (PMID 21152186, 2011).
breast carcinoma (4 papers, 2009 to 2023). "By MSRE-PCR, we identified abnormal hypermethylation of promoter CpG dinucleotides of five MMP genes, MMP2, MMP23B, MMP24, MMP25, and MMP28, in breast cancer." (PMID 32397602, 2020). "For MMP-28 five bands at approximately 62, 58, 50, 48 and 46 kDa were detected and all of them showed a significantly higher expression in breast cancer tissue, either grade 2 or grade 3, when compared to normal breast tissue." (PMID 19531263, 2009). "In our collection of 183 breast cancer samples, abnormal hypermethylation was observed for CpGs in MMP2, MMP23B, MMP24, MMP25, and MMP28 promoter regions." (PMID 32397602, 2020).
colon carcinoma (4 papers, 2006 to 2023). "Cancer-by-cancer, lung squamous (LUSC) has two MMPs with sensitivities over 95% (MMP11 and MMP12), colon cancer (COAD) has three over 94% (MMP11, MMP28, and MMP7), and esophageal cancer (ESCA) has two over 94% (MMP11 and MMP12)." (PMID 31200666, 2019). "Similarly, another study reported the role of MMP28 in inducing EMT by degrading E-cadherin, thereby promoting metastasis in colon cancer." (PMID 37835389, 2023). "Similarly, a detailed analysis of genes downregulated in tumor samples resulted in the identification of protease genes including MMP28, ANPEP, ADAMTS1 and ADAMTS15, previously known to be repressed in colon carcinoma or in other tumor types." (PMID 24243807, 2013).
lymph node metastasis (3 papers, 2011 to 2025). "Moreover, MMP28 upregulation was associated with the advanced American Joint Committee on Cancer (AJCC) stage and lymph node metastasis (P < 0.05)." (PMID 39972459, 2025).
osteoarthritis (3 papers, 2009 to 2018). A noninflammatory degenerative joint disease occurring chiefly in older persons, characterized by degeneration of the articular cartilage, hypertrophy of bone at the margins and changes in the synovial membrane. "Recent research has shown the presence of MMP28 in cartilage and synovium; MMP28 was one of the four most significantly upregulated genes in osteoarthritis, suggesting a role for MMP28 in association with cartilage degradation and/or regeneration." (PMID 20003223, 2009). "However, increased levels of MMP28 could be detected in cartilage from osteoarthritis and rheumatoid arthritis patients, suggesting that this novel MMP plays a certain, not completely understood role in some musculoskeletal diseases." (PMID 21801383, 2011). "Interestingly, MMP28 expression seemed to be increased in osteoarthritis and degenerated IVD compared to healthy tissue, indicating that it may play an important role during these disease processes." (PMID 21801383, 2011). "(Unfortunately, the work of Kevorkian and colleagues and that of Davidson and colleagues in osteoarthritis did not include immunohistochemical studies of the cartilage matrix, so we do not know whether ECM localization of MMP28 was present)." (PMID 20003223, 2009).
bladder cancer (2 papers, 2006 to 2023). "Our work confirms the importance of well-documented genes, such as MMP-2 and MT1-MMP, but also highlights several new proteases including MMP-28, whose localisation and function in early bladder cancer is under-investigated." (PMID 16465195, 2006).
cervical cancer (2 papers, 2010 to 2011). A primary or metastatic malignant neoplasm involving the cervix. "Lastly, all three cervical cancer cell lines four protein bands of approximately 62, 50, 48 and 46 kDa were found for MMP-28." (PMID 20942921, 2010).
disc degeneration (2 papers, 2009 to 2011). "Our results indicate that MMP28 is expressed by human intervertebral disc cells in vivo and in vitro, with high donor-donor variations in vivo but did not depend on the level of disc degeneration as measured by Thompson grade score." (PMID 21801383, 2011).
emphysema (2 papers, 2022 to 2023). "mmp28−/− mice are protected from inflammation and emphysema caused by tobacco smoke since MMP-28 is critical for leukocyte recruitment into chronic smoke-exposed lungs; indeed, neutrophil adhesion receptors and chemokines are reduced in mmp28−/− mice." (PMID 35805895, 2022). "Thus, MMP-28 appears to promote the inflammatory response in the pathogenesis of emphysema, although its specific contribution and mode of action remain to be elucidated." (PMID 36835197, 2023). "MMP-28, like MMP-10, plays a causative role in cigarette-smoke-induced emphysema." (PMID 36835197, 2023).
multiple sclerosis (2 papers, 2008 to 2017). A progressive autoimmune disorder affecting the central nervous system resulting in demyelination. "Further characterization of MMP-28 protein expression in diseased human samples will help to clarify the extent of MMP-28 involvement in multiple sclerosis, however, these results demonstrate that in mouse EAE and human MS tissues, an increase in axon associated MMP-28 can be detected." (PMID 18778487, 2008). "MMP-28 protein expression was increased within demyelinated lesions of mouse experimental autoimmune encephalitis (EAE) and human multiple sclerosis lesions compared to surrounding normal tissue." (PMID 18778487, 2008).
oral squamous cell carcinoma (2 papers, 2011 to 2023). "The expression of MMP28 is increased in oral squamous cell carcinoma (OSCC) compared to premalignant lesions." (PMID 21615884, 2011). "Few studies have investigated expression of MMP28 in human tumor samples; however, it is overexpressed in oral squamous cell carcinoma." (PMID 21615884, 2011). "Knockdown of MMP28 leads to inhibition of anchorage independent growth in both OSCC (oral squamous cell carcinomas)and esophageal carcinomas." (PMID 21615884, 2011).
bladder tumour (1 paper, 2006). "This study showed that MMP2, MT1-MMP, and MMP28 were very highly expressed in bladder tumour samples and MMP1, 7, 9, 11, 15, 19, and 23 were also highly expressed." (PMID 16901349, 2006).
cholangiocarcinoma (1 paper, 2022). A carcinoma that arises from the intrahepatic biliary tree (intrahepatic cholangiocarcinoma) or from the junction, or adjacent to the junction, of the right and left hepatic ducts (hilar cholangiocarcinoma). "In addition, WTAP overexpression in cholangiocarcinoma induced the expression of metastasis-related genes such as cathepsin H, matrix metallopeptidase 7 (MMP7), matrix metallopeptidase 28 (MMP28), and mucin 1 (Muc1); however, the specific regulatory mechanisms have not been investigated." (PMID 36139062, 2022).
demyelinating disease (1 paper, 2008). A broad group of disorders that affect the myelin sheaths that cover the neurons. "If MMP-28 activity plays a similar role in modulating myelination in vivo, inhibition of this protease may represent a therapeutic mechanism for enhancing remyelination in demyelinating diseases." (PMID 18778487, 2008).
diabetes (1 paper, 2021). "Our data indicate that the observed changes in heart functional parameters due to increased obesity and diabetes development could be associated with the observed decrease of MMP-28." (PMID 33923282, 2021). "MMP-2 was upregulated, MMP-9 was unchanged, and MMP-28 was downregulated in consequence of diabetes development." (PMID 33923282, 2021). "Collagen I is a potential endogenous substrate for MMPs, and the diabetes-induced changes may reflect the observed downregulation of MMP-28 or activation of tissue 72 kDa MMP-2." (PMID 33923282, 2021). "The findings of the current study also demonstrate that diabetes development involves changes in MMP-2 and MMP-28 and attenuation of antioxidant defense by SOD." (PMID 33923282, 2021). "The application of quercetin did not change MMP-28 protein levels in control lean animals, and also did not influence the diabetes-induced effects on cardiac MMP-28." (PMID 33923282, 2021). "In accordance with this is the fact that quercetin treatment did not modulate negative effects of diabetes on heart functional parameters as well as on MMP-28." (PMID 33923282, 2021).
diabetic cardiomyopathy (1 paper, 2023). Diabetic cardiomyopathy is a disorder of the heart muscle in people with diabetes. "Indeed, MMP28 is markedly downregulated in the left ventricle of aged obese diabetic Zucker Diabetic Fatty (ZDF) rats compared to control lean rats, suggesting the role of MMP28 in heart function and a potential involvement of impaired MMP28 action in diabetic cardiomyopathy." (PMID 37445827, 2023).
gastric tumors (1 paper, 2011). "This study demonstrates MMP28 protein is overexpressed in gastric tumors (30/30, 100%) compared to normal epithelia (16/30, 53.3%, p < 0.001)." (PMID 21615884, 2011).
influenza (1 paper, 2011). An acute viral infection of the respiratory tract, occurring in isolated cases, in epidemics, or in pandemics; it is caused by serologically different strains of viruses (influenzaviruses) designated A, B, and C, has a 3-day incubation period, and usually lasts for 3 to 10 days. "Furthermore, Mmp28-/- mice demonstrate increased susceptibility to influenza-induced respiratory epithelial cell apoptosis." (PMID 22040290, 2011). "Because influenza infection targets the airway epithelium and leads to epithelial cell apoptosis, we assessed if influenza infection led to increased apoptosis in Mmp28-/- epithelium." (PMID 22040290, 2011). "Furthermore, we found that MMP28 mRNA expression from influenza-challenged whole lung was unchanged in early infection (days 1-2) and decreased at later timepoints (days 3-5), in contrast to other MMPs -3,-7,-12." (PMID 22040290, 2011). "Despite differences in epithelial cell apoptosis at 3 days, we found that influenza virus levels were similar at all time-points in Mmp28-/- and wild-type mice, suggesting that MMP28 is not required for control of influenza infection." (PMID 22040290, 2011).
ischemia (1 paper, 2022). A hypoperfusion of the BLOOD through an organ or tissue caused by a PATHOLOGIC CONSTRICTION or obstruction of its BLOOD VESSELS, or an absence of BLOOD CIRCULATION. "In contrast, transcriptomic levels of Mmp11, Mmp23, and Mmp28 exhibited a bimodal pattern: their mRNA expression was downregulated in the first 24 h after ischemia, whereas significant upregulation was observed in the infarcted tissue isolated from day seven to day 21 post-MI." (PMID 36555255, 2022).
keloid (1 paper, 2007). An irregularly shaped, elevated mark on the skin caused by deposits of excessive amounts of collagen during wound healing. "A lower expression of MMP-28 and elevated expression of TIMP-3 in leiomyomas compared to keloids imply a lower matrix turnover with an increase angiogenic and pro-apoptotic activities that has been associated with TIMP-3." (PMID 17718906, 2007). "A number of MMPs were equally expressed in leiomyomas, keloids and peritoneal adhesions with the exception of lower MMP-14, MMP-24 and MMP-28 expression in leiomyomas, suggesting that these tissues are potential target of their proteolytic actions." (PMID 17718906, 2007).
leiomyoma (1 paper, 2007). A well-circumscribed benign smooth muscle neoplasm characterized by the presence of spindle cells with cigar-shaped nuclei, interlacing fascicles, and a whorled pattern. "The biological importance of lower expression of these MMPs in leiomyoma is unknown; however unlike most MMPs that are secreted as inactive proenzymes and require activation, MMP-11 and MMP-28 are secreted in active forms." (PMID 17718906, 2007).
metastatic tumors (1 paper, 2022). "Furthermore, an analysis of matched normal mucosa, primary CRC and CRC liver metastasis demonstrates and an increase in expression of CD36 and MMP28 and a decrease in the expression of E-cadherin as we move from normal tissues to primary and metastatic tumors." (PMID 35008415, 2022).
Obesity (1 paper, 2021). Accumulation of substantial excess body fat. "Results showed that obesity worsened heart function and this was associated with MMP-2 upregulation, MMP-28 downregulation, and inhibition of superoxide dismutases (SODs)." (PMID 33923282, 2021). "By the study of molecular mechanisms underlying the effects of obesity development and possible actions of QCT in aged lean and obese ZDF rats we observed the potential role of MMP-2 and MMP-28." (PMID 33923282, 2021). "In conclusion, worsened heart function due to obesity involved changes in MMP-2 and MMP-28 and attenuation of antioxidant defense by SOD." (PMID 33923282, 2021).
pterygium (1 paper, 2021). A wedge-shaped fibrovascular lesion arising from the bulbar conjunctiva and extending to the cornea. "In this study, multiple types of MMPs (MMP2, MMP3, MMP8, MMP9, MMP11, MMP16, and MMP28) were highly expressed in pterygium." (PMID 33790949, 2021).
ST Elevation Myocardial Infarction (1 paper, 2020). A myocardial infarction that produces elevation in the ST segments of the ECG. "The MMP-28 levels were significantly higher in patients with acute ST-elevation myocardial infarction (STEMI) than in patients with non-ST-elevation myocardial infarction (NSTEMI) (P < 0.01)." (PMID 32596395, 2020). "The levels of NT-proBNP, hs-CRP, and MMP-28 were significantly higher in patients with acute ST-elevation myocardial infarction (STEMI) than in patients with non-ST-elevation myocardial infarction (NSTEMI) (P < 0.01)." (PMID 32596395, 2020).
tongue squamous cell carcinoma (1 paper, 2008). A squamous cell carcinoma that arises from the tongue. "We found a slight trend between positive MMP-28 immunostaining and better prognosis of tongue squamous cell carcinoma." (PMID 18253113, 2008).
urolithiasis (1 paper, 2023). Stone(s) within the urinary tract. "For LASSO regression analysis, six variables, MMP1, MMP3, MMP9, MMP10, MMP27 and, MMP28, were screened as diagnostic markers for urolithiasis." (PMID 37006258, 2023).